CD4 (CD4 molecule)
Diseases named in the same sentence as CD4 in open-access papers (continued):
Sharing a sentence is not in itself a finding about the gene and the disease.
cancer (continued). "However, limited clinical evidence was found regarding the predictive value of naïve CD4+ T cell infiltration for immunotherapy in cancer patients, which needs to be further explored in future studies." (PMID 38502852, 2024). "IFN-g may not only affect the cell cycle of cancer cells, but also enhance further infiltration of CD4+ T cells." (PMID 39106430, 2024). "Because of the lack of sufficient evidence, it is unknown whether the exosomes from other antitumor cells (such as CD8+ T cells, CD4+ T and B cells) in tumors can be used as cancer vaccines or drug delivery system." (PMID 38585234, 2024). "Thus, CD4 + helper T cells are responsible for facilitating many cellular and humoral immune responses against pathogens and cancer." (PMID 39155358, 2024). "Generation of CD4+ T cells is critical for the formation CD8+ T effector cells and CD8+ T memory cells during the antitumor immune response that is closely associated with antitumor immunity in many cancers." (PMID 39898278, 2024). "The MAN1C1High samples exhibited an increase in the release of cancer cell antigens (Step 1) and the trafficking of immune cells, including T cells, CD4 + T cells, CD8 + T cells, Th1 cells, DCs, Th22 cells, MO, monocytes, neutrophils, NK cells, basophils, Tregs, and MDSCs, to tumors (Step 4)." (PMID 39333557, 2024). "Notably, AURKB expression was positively correlated with CD4+ Th (T‐helper) 2 cells in all cancers except TGCT." (PMID 38898693, 2024). "CD8+ TLs target cancer cells and inhibit angiogenesis, while CD4+ TH2 cells support B lymphocytes." (PMID 39765634, 2024). "Since, several studies indicated that a higher CD4+, CD8+ T cell infiltration scores were associated with better survival in cancers, it is reasonable that high expression of SPOP may recruit more TICs and result in a better survival." (PMID 39074086, 2024). "Meanwhile, immune infiltration analysis revealed that expression of LGALS3 showed a significant positive association with several immune cell populations, involving CD4+ T cell, CD8+T cell, B cell, neutrophil, macrophage, dendritic cell, as well as cancer-associated fibroblasts (CAFs) within HCC." (PMID 38643145, 2024). "CD4+ Treg cells derived from tumors have been extensively examined in numerous cancer types." (PMID 39664195, 2024). "Notably, CD34, IL7R, NRP1, GZMB, FGF7, and ENO2 exhibited significant expression in cancer stem cells, CD4+ memory cells, regulatory T cells, NK cells, fibroblasts, and neurons, respectively." (PMID 38846945, 2024). "Patients with malignancy of the lung, breast, colon, bladder, head–neck, prostate, rectum, and esophagus were found to have lower percentage of CD4+ and CD8+ T cells compared to those who had received four doses of the mRNA vaccine or those patients on hemodialysis." (PMID 39066390, 2024). "CD8+ T cells are major drivers of the anti-cancer immune response, utilizing granzymes and perforins to kill the target cancer cells, while CD4+ T cells contribute to the anti-cancer immune response through CD8+ T cell priming and the activation of innate immune cells." (PMID 38398074, 2024). "Furthermore, we detected an inverse relationship between the GSVA ESs of iAge-CRGs and the levels of naïve CD8+ and CD4+ T cells, neutrophils, and B cells across various types of cancer." (PMID 38714870, 2024). "Additionally, SELENOI expression was positively correlated with CD4+ T cells and negatively correlated with macrophages in most cancers (p < 0.05)." (PMID 39669976, 2024). "CD4+ T cells are crucial in creating an immunogenic environment in various cancers." (PMID 39409930, 2024). "When adding one unknown to the model, the observed trend remained unchanged, but the CESC and CD4/8+ T cell contributions were entirely transferred to the unknown components, and the contributions from other cancer types were strongly attenuated." (PMID 39177091, 2024).
cancer (continued). "Furthermore, Cancer Region 2 contained a higher proportion of naïve CD4+ T cells, gamma delta T cells, M0 macrophages, and eosinophils, while Cancer Region 1 contained a higher proportion of activated NK cells." (PMID 39858416, 2024). "Indeed, the correlation between CD4 nadir and disease progression to cancer has recently been demonstrated." (PMID 39770774, 2024). "Because of their suppressive effect on the immune system in cancer, the development of MDSCs and their interaction with CD4+ T cells could be beneficial for antigen-specific immunotherapy." (PMID 38988152, 2024). "For example, CD8+ T cells, broadly encompassing memory and naïve compartments, have positive prognostic value in many cancer types, whereas regulatory T cells, a specific subset of CD4+ T cells, generally have negative prognostic associations." (PMID 39191725, 2024). "In some cases, low CD4 counts are due to cancer therapy, therapeutics, or unknown etiology and while the risk of developing infections or cancer still exists, the frequency is less." (PMID 39430110, 2024). "The enhanced infiltration of CD4+/CD8+ T cells may have contributed to the improved cancer regression in the combination therapy group." (PMID 38175694, 2024). "Moreover, the two groups exhibited greater differences in the CD4+ T cell subset infiltration levels in these cancers, with smaller differences observed in the CD8+ T cell subsets." (PMID 39555091, 2024). "We finally assessed whether a combination of sLAG3 concentrations and the CD4/CD8 ratio values as important modulators of the antitumoral response might pose as outcome predictors of patients with advanced cancer under ICI therapy." (PMID 38233492, 2024). "In a contradictory fashion, the cell subtype Th2 CD4+ instead promotes tumorgenicity and encourages metastasis by releasing cytokines IL-4, IL-5, and IL-13, but it also releases IL-10, which can influence either the growth or destruction of cancer cells." (PMID 39050852, 2024). "Long MHC II peptides (approximately 30 amino acids) have gained considerable attention in the drug discovery process; these long MHC II peptides, once injected, are captured by DCs and presented to CD4 + cells, which are activated and selectively kill cancer cells." (PMID 39720956, 2024). "Conventional DC type 1 and 2 (cDC1 and cDC2) prime CD8+ and CD4+ T cell subsets, respectively, toward viral infections and cancer via antigen-loaded major histocompatibility complexes (MHC) to activate T cell responses towards the corresponding antigen of interest." (PMID 38646527, 2024). "The prognostic role of low CD4:CD8 ratio and elevated CD8 cell counts on the risk of cancer remains unclear." (PMID 38092042, 2024). "Specific TIL subsets that have been shown to be associated with cancer prognosis vary across the studies and include CD3+, CD4+, CD5+, CD8+, CD45RA+, FOXP3+ and PD1+ TILs; however, CD3+, CD8+ and FOXP3+ TILs were commonly shown to associate with prognosis in many cancer types." (PMID 38704243, 2024). "The critical roles of CD4+ T cells have been understudied for cancer vaccines." (PMID 38519525, 2024). "CD4+ T cells were essential in both innate and antigen-specific immune responses, and play a crucial role in mobilizing the immune system against cancer cells​." (PMID 38408977, 2024). "However, we found evidence for cDC1 licensing by IFN-I-producing CD4+ T cells in the TME of multiple cancer types with T-cell infiltration, which correlated with the response to PD-1 blockade and overall patient survival." (PMID 38383773, 2024). "As enhanced TFH cell differentiation in a TMBHigh mouse cancer model has been shown to induce larger TLSs and superior B-cell recruitment, we next determined the density of CD4+CXCR5+PD1+FoxP3− TFH cells in HGSOC and NSCLC samples using multiplex immunofluorescence." (PMID 38514660, 2024).
cancer (continued). "Our analysis revealed significant positive correlations between S100 score and regulatory T cells, Dendritic cells resting, Neutrophils, Mast cells activated, Macrophages M0, Macrophages M1, T cells CD4 memory activated and Macrophages M2 across most cancer types." (PMID 38684596, 2024). "We observe that approximately 1–5% of CD4+ T cells from the blood of people living with HIV-1 exhibit over-duplicated centrioles, suggesting that centrosome amplification underlies the development of HIV-1-associated cancers by driving aneuploidy." (PMID 38443376, 2024). "Although HIV may accelerate the growth of HPV-related cancers by reducing CD4+ T cells, this mechanism is still up for debate." (PMID 39902182, 2024). "The abundance of CD4 naïve T cells and Tregs is closely correlated, both indicating poor prognosis for cancer patients, which might contribute to resistance to neoICT in non-pCR group." (PMID 39334513, 2024). "Our review further revealed that lower CD4 cell counts < 200 cell/μl was also noted as a prevalent risk for ADCs, NADCs, and associated mortality highlighting the role that immunosuppression plays in predisposing PLHIV to cancer." (PMID 38549952, 2024). "The cytokine response in peripheral CD4+ T cells was upregulated during the carcinoma process." (PMID 38343544, 2024). "In addition, senescent T-cells in elderly cancer patients were significantly higher than in younger ones (p=0.025, p=0.0002, for CD4 and CD8 respectively)." (PMID 37334387, 2023). "The presence of cytotoxic CD4 T cells that have shared TCR clones with multiple helper T cell subsets suggests that the cytotoxic function in CD4 T cells is regulated independently of their helper function in cancer." (PMID 37654482, 2023). "The CD4 count at time of cancer diagnosis was also assessed." (PMID 37509301, 2023). "The roles of CD8+ and CD4+ T cells in cancer vaccine therapy are well established." (PMID 36992127, 2023). "Thus, a more comprehensive understanding of the roles of CD4+ T cells and B cells is crucial for more robust development of cancer immunotherapy." (PMID 38077321, 2023). "A heightened presence of activated memory CD4 T cells within the TIME has been associated with the facilitation of robust immune responses, thereby substantially enhancing the overall prognosis for individuals afflicted by cancer." (PMID 38066437, 2023). "As a result, 176,371 CD4+ T cells from 8 cancer types were used for downstream analysis." (PMID 36049666, 2023). "In paracancerous tissues, the weak expression rate of CD4 was 38.75% (24 out of 62), while the moderate and high intensity expression rates were 0.In cancer tissues, CD8 expression was weak in 48.4% (30/62) of cases, moderate in 38.7% (24/62) of cases, and high in 12.9% (8/62) of cases." (PMID 37881431, 2023). "In addition, phosphoenolpyruvate carboxykinase 1 (PCK1) catalyzes the conversion of oxaloacetate (OAA) into PEP, and the overexpression of PCK1 enhances the cancer-killing functions of adoptive transferred CD4+ and CD8+T-cells." (PMID 36768924, 2023). "Importantly, Tregs constitute a key CD3+CD4+ subset that inhibits an effective anti-cancer immune response by producing the immunosuppressive cytokines IL-10 and TGF-β and consuming IL-2." (PMID 36980527, 2023). "Indeed, peptide-specific cytotoxic responses by CD4+ CTLs have been described towards multiple viruses and cancers." (PMID 37122720, 2023). "We could determine 79 cell types by separately clustering the CD4+ T cells in each cancer type, ranging from 7 to 12 cell types in each cancer type." (PMID 36049666, 2023). "On the other hand, CD4-2D3 cell line is useful to identify the antigens specific for the TCRs isolated from the CD4+ T cells that dominantly and clonally existed in patients with cancer, infectious, inflammatory, or auto-immune diseases." (PMID 36939853, 2023). "CD3+/CD4+/CD8+ MF was found to be more aggressive than CD3+/CD4+/CD8- MF cancers." (PMID 37829962, 2023).
cancer (continued). "We showed that the Rs had significantly fewer CD3+, CD8+ and CD56+ lymphocytes than the PTs, but that the amounts of CD4+ cells remained similar in the PTs and the Rs, suggesting that CD4+ cells could play an important role in cancer immunoescape." (PMID 36627701, 2023). "CD4+ T cells have also played a pivotal role in cancer induced by viruses." (PMID 37063862, 2023). "Our results demonstrated that, except for the upregulation of sPD-L1, PD-1 expression on peripheral CD4+T cells, and the apoptotic rate of peripheral PD-1+cells and PD-1+CD4+T cells were significantly increased in patients with cancer compared with healthy donors." (PMID 37266424, 2023). "Moreover, the type and density of TIICs in the TME affect the survival outcomes of cancer patients; for example, reduced CD4+ central memory T cells and natural killer (NK) cells were significantly associated with better survival in glioblastoma patients." (PMID 36769082, 2023). "CD4+ T cells play an important role in immune responses against pathogens and cancer cells." (PMID 37965314, 2023). "In conclusion, first, CD4-2D3 cell line will make it possible to identify the antigens specific for the antigen-unknown TCRs isolated from cancer, inflammatory, and autoimmune lesions." (PMID 36939853, 2023). "However, CD4 memory resting cells can also promote the growth and progression of cancer by promoting angiogenesis and remodeling of the extracellular matrix." (PMID 37465677, 2023). "Some markers CD14 (monocyte), CD3D (CD4+T cells), CD3E (CD8+T cells), CD68 (macrophage), CST3 (myeloid cells), GNLY (NK cells), KRT18 (epithelial cells), and NKG7 (NK cells) were positively associated with TMSB10 in all cancers." (PMID 37275863, 2023). "Moreover, there is a higher survival rate of CD45+/CD3+/CD4+/CD8+ T cells in PDA‐modified scaffolds for potential cancer immunotherapy drug screening." (PMID 37424037, 2023). "The extensive CD4+T cells determined poor clinical outcome in Caprin-1high patients, arguing that highly expressed Caprin-1 may assist cancer cells to escape from immune surveillance." (PMID 38082307, 2023). "Moreover, a substantial enrichment of CD4+, CD4+PD‐1+, and Foxp3+ phenotypes cell populations near cancer cells were observed in UnTx compared to IP CD40 and NDES CD40 (dotted black rectangle; rows 11, 12, and 13, respectively, and column 21)." (PMID 36658712, 2023). "LncRNAs regulating CD4+ T cell subsets during homeostasis and cancer." (PMID 37346034, 2023). "This shift toward a higher CD4/CD8 T cell ratio in mice bearing St6galnac4−/− tumors is similar to the trend observed in the immune system of healthy patients compared to those with cancer." (PMID 36897988, 2023). "Therapeutics aiming to reverse T‐cell exhaustion by targeting PD‐1 are becoming popular, and a recent paper highlighted that patients with cancer treated with anti‐PD‐1 immunotherapy had an increase in proliferation within their PD‐1 expressing CD4+ T follicular helper cells." (PMID 36975169, 2023). "Finally, 6 COAD patients with high expression of FDX1 were screened, and the proportion of CD8+ T cells in cancer tissues of these patients was significantly higher than that in paracancerous, while the CD4+ T cells presented the opposite pattern." (PMID 36173462, 2023). "mRNA vaccines mediate antigen presentation, as they are incorporated by dendritic cells, which consequently express the vaccine-encoded cancer antigens on their surface, thus inducing cytotoxic CD8+ as well as helper CD4+ cell activation while increasing the release of inflammatory mediators." (PMID 36992220, 2023). "Additionally, we observed a negative correlation between GSVA-ES of ECM-SRGs and naive CD8 and CD4 T cell, neutrophil, and B cells in pan-cancer (P-value and FDR ≤ 0.05)." (PMID 37985530, 2023). "Interestingly, the SSGSEA algorithm showed that the CD4/CD8 cell ratio in the high risk score group is much higher, indicating a lost response to the cancer cells of the immune system." (PMID 39188277, 2023).
cancer (continued). "Thus, cancer cells outcompete CD4 T cells for methionine and impair antitumor immunity in association with PD-1 upregulation in CD4 T cells." (PMID 37147330, 2023). "The expression of DHX9 was significantly associated with the abundance of infiltrating immune cells: B cells in 17 cancers, CD8+ T cells in 22 cancers, CD4+ T cells in 12 cancers, neutrophils in 31 cancers, macrophages and myeloid dendritic cells in 18 cancers." (PMID 37214432, 2023). "However, cancer patients exhibited different results in this study, the ratio of CD4+/CD8+ T cells kept balance with age growing." (PMID 38102684, 2023). "For example, CCL22 and TGF- β produced by the cancer cells and cancer-associated fibroblasts could recruit Tregs which in turn produce TGF-β and induce the conversion of naïve CD4+ T cells into Tregs." (PMID 38264664, 2023). "Nevertheless, CD4+ T cells are crucial for destroying cancer." (PMID 38067231, 2023). "From May 8, 2018, to December 10, 2021, twenty-four patients with HIV and advanced cancer as well as a CD4+ T-cell count greater than or equal to 100 cells/μL were treated with camrelizumab in daily practice." (PMID 37062823, 2023). "In the first half of the monitoring period, the absolute number of TMEM123+ CD8+T cells interacting with cancer cells was slightly higher than TMEM123+ CD4+ T cells (up to 1.6-fold at 24h), whereas afterwards both cell types reached a plateau with comparable numbers." (PMID 37426665, 2023). "Furthermore, they showed that the upregulation of CD4 expression in T cells in the ITME was positively associated with high cancer grade, cancer stage, and myometrium invasion." (PMID 37927462, 2023). "In addition, the number of CD8 + T cells in the matrix and the cancer cell nest is related to one another, and the synergy between CD4+and CD8+ T cells is closely related to the prognosis of ESCC patients." (PMID 36891293, 2023). "Cancer grade correlated negatively with CD4+ count at baseline (r = − 0.4856, p = 0.0300)." (PMID 37085562, 2023). "Although their role has not yet been defined in patients with cancer, coexpression of markers on subsets of CD4+ T cell EMRA thought to be due to exhaustion was associated with AML relapse." (PMID 36968223, 2023). "tsMHC-II positive cancer cells may act as surrogate antigen-presenting cells and targets for CD4+ T cell–mediated lysis." (PMID 37565053, 2023). "Therefore, further research is needed to understand better the function of CD4+ cells and their role in cancer immune escape." (PMID 36627701, 2023). "Therefore, stimulating CD4+ T cells is crucial to achieving long-term antitumor immune memory in cancer immunotherapy." (PMID 37082269, 2023). "However, compared with most cancer patients, the unique clonotypes of healthy donors were abundant in naïve cells (including CD4 + and CD8 +), while fewer were in Treg cells." (PMID 37024957, 2023). "According to the patient’s age, SIP expression on CD4 T-cells was associated with lower serological response in the young cancer patient population, but not in the elderly." (PMID 37334387, 2023). "However, CD4+ T cells accounted for 35.70 ± 13.40% of total lymphocytes in cancer tissues, significantly lower than 49.62 ± 4.67% in paracancerous tissues (P < 0.01)." (PMID 36173462, 2023). "Moreover, PVRIG had a significant positive expression correlation with the ratios of CD8+/CD4+ regulatory T cells in pan-cancer and in 29 individual cancer types (Pearson correlation, FDR < 0.05)." (PMID 37542274, 2023). "First, neoantigen-specific CD4+ T-cell reactivity is common in human cancers." (PMID 36979775, 2023). "Adora2b on CD4+ T cells contributes to immunosuppression and could be a target in cancer, but additional studies are needed to learn more about the role of the receptor on CD4+ T cells." (PMID 37187740, 2023). "First, studies suggest that in both murine models and human cancers, NeoAg-specific CD4+ T cells may be more abundant than NeoAg-specific CD8+ T cells." (PMID 37400675, 2023).